Y_RNA (Y RNA )
Gene: Miscellaneous RNA gene on chromosome 2 (121,040,610 to 121,040,710, reverse strand). Ensembl gene ENSG00000201584.
Homologues: Orthologues: chimpanzee Y_RNA (100% identical), macaque Y_RNA (93% identical). Paralogues in human: Y_RNA (93% identical), Y_RNA (92% identical), Y_RNA (91% identical), RNY3 (90% identical), Y_RNA (90% identical), Y_RNA (89% identical), Y_RNA (88% identical), RNY3P1 (87% identical), RNY3P2 (87% identical), Y_RNA (87% identical), RNY3P14 (86% identical), Y_RNA (86% identical), and 95 more.